EZH2 (enhancer of zeste 2 polycomb repressive complex 2 subunit)
Diseases named in the same sentence as EZH2 in open-access papers (continued):
Sharing a sentence is not in itself a finding about the gene and the disease.
prostate adenocarcinoma (16 papers, 2013 to 2025). "EZH2 was overexpressed in tumors compared to the normal tissues in most of them, including prostate adenocarcinoma (PRAD) (p-value < 0.001)." (PMID 36358967, 2022). "In human prostate, a minor subgroup of “stem” cells (CD44+, Oct4+) expresses EZH2 and has been proposed to represent a cell reservoir for prostatic adenocarcinoma initiation." (PMID 23675307, 2013). "Collectively, our data clearly demonstrate the importance for EZH2 catalytic function to govern expression/action of MR-TFs that drive phenotypic plasticity and cell state transitions allowing prostate adenocarcinoma evolution to NEPC to evade AR signaling inhibitors." (PMID 40832297, 2025). "Additionally, we observed that EZH2 inhibition suppressed inflammatory signaling, consistent with prior work suggesting that inflammatory reprogramming is required for lineage transition from prostate adenocarcinoma to NEPC." (PMID 40832297, 2025). "EZH2 and REST clearly have opposite functions and expression patterns in NEPC compared to prostate adenocarcinoma." (PMID 38777812, 2024). "Additional work has demonstrated that metformin can also suppress epigenetic modifier, enhancer of zeste homolog 2 (EZH2), in its anti-cancer activity in prostate adenocarcinoma and neuroendocrine tumors." (PMID 35631452, 2022). "The strongest correlation between high mRNA abundance and poor survival was observed for EZH2 and EED in prostate adenocarcinoma (logrank p < 0.01; hazard ratio 6.52 and 5.16, respectively)." (PMID 34202528, 2021). "In prostate adenocarcinoma, this non-canonical function of EZH2 can collaborate with the AR transcriptional machinery to drive AR-signaling or with N-myc to modulate plasticity." (PMID 38405800, 2024). "The Beltran group recently published a study confirming that in NEPC, EZH2 has non-canonical functions compared to its canonical roles in prostate adenocarcinoma." (PMID 39682746, 2024). "Here we demonstrated that along with prostate adenocarcinoma, other tumor types show a correlation between high EZH2, SUZ12 and EED levels and a shorter survival, suggesting that these cancers could be potential targets for EZH2/SUZ12/EED inhibitor therapy." (PMID 34202528, 2021).
uveal melanoma (16 papers, 2012 to 2024). A melanoma derived from melanocytes of the uveal tract. "Although many studies have described EZH2 and H3K27me3 in different cancers, it is unclear whether the EZH2 mutation exists in uveal melanoma and the effect of EZH2 and H3K27me3 in uveal melanoma." (PMID 36276954, 2022). "We aim to determine the predictive value and potential therapeutic target of EZH2 in uveal melanoma." (PMID 36276954, 2022). "miRNA-124a has been shown to function as a tumor suppressor by targeting Receptor for Activated Protein C Kinase (RACK1) in cutaneous melanoma and the histone methyltransferase Enhancer of Zest Homolog 2 (EZH2) in uveal melanoma." (PMID 35480113, 2022). "In accordance with the mRNA level, EZH2 protein expression in uveal melanoma cells was higher than that in normal ocular cells, and the same result was detected for H3K27me3 expression." (PMID 36276954, 2022). "We found that EZH2 (41/85, 48.24%) and H3K27me3 (49/85, 57.65%) were overexpressed in uveal melanoma." (PMID 36276954, 2022). "To determine the correlation of the expression of EZH2 and H3K27me3 in uveal melanoma, we applied Spearman analysis, which demonstrated the expression of EZH2 and H3K27me3 was significantly positively correlated (r = 0.446, p < 0.01)." (PMID 36276954, 2022). "HOXA11-AS can increase uveal melanoma cell growth and invasion by interacting with enhancer of zeste homolog 2 (EZH2) to suppress its target p21 protein expression and by sponging miR-124." (PMID 29244840, 2017). "While EZH2 has previously been shown to bind CIITApIV in malignant uveal melanoma cells, mechanistic roles for EZH2 in regulating CIITA and MHC II expression remain to be elucidated." (PMID 22563434, 2012). "EZH2 is reported to be a direct target of miR-26a in Uveal Melanoma (UM) cells." (PMID 36873948, 2023). "Notably, all uveal melanoma (UVM) cases with EZH2 gene alterations had only the ‘deep deletion’ type." (PMID 36545914, 2023). "Therefore, it is necessary to identify the overexpression of EZH2 and its therapeutic potential in uveal melanoma." (PMID 36276954, 2022). "Our study demonstrated that EZH2 and H3K27me3 were overexpressed in uveal melanoma." (PMID 36276954, 2022). "To investigate the importance of EZH2 in uveal melanoma cells, we examined several small-molecule methyltransferase inhibitors, including UNC 1999, EPZ6438, GSK126, and GSK503, and the embryonic ectoderm development protein (EED) inhibitor EED226 in OMM1 cells." (PMID 36276954, 2022). "miR-32 is recently shown to target EZH2 and is down regulated in uveal melanoma." (PMID 27846237, 2016). "This could represent a possible connection between BAP1 and expression of HLA in uveal melanoma, as study in mice showed that loss of BAP1 leads to increased levels of EZH2 (and PRC2) with repressed expression of its targets, including thus CIITA, leading ultimately to less HLA class II expression." (PMID 27764126, 2016). "Notably, it has been reported that sensitivity of uveal melanoma to EZH2 inhibitors is independent of BAP1 mutational status, suggesting a lineage-specific effect of BAP1 on the activity of EZH2i (EZH2 inhibitors)." (PMID 33072611, 2020).
autoimmune disease (15 papers, 2015 to 2025). A disorder resulting from loss of function or tissue destruction of an organ or multiple organs, arising from humoral or cellular immune responses of the individual to their own tissue constituents. "EZH2 has a pathogenic role in several particular autoimmune diseases including rheumatoid arthritis, type I diabetes, systemic lupus erythematosus, multiple sclerosis, and IBD." (PMID 37158530, 2023). "Evidence suggests that EZH2 is implicated in the pathogenesis of autoimmune diseases, including SLE, RA, and psoriasis (PsA)." (PMID 35795677, 2022). "have demonstrated that Ezh2 is involved in stabilizing the expression of Foxp3 in a mice model, selective deletion of Ezh2 in CD4+Treg resulted in the development of autoimmune diseases and accompanied by reduced stability of CD4+Treg." (PMID 38250084, 2023). "In infection models and autoimmune disease models, EZH2 inhibits the expression of genes and signaling pathways involved in anti-inflammatory function, such as PPARγ, SOCS1, STAT6, etc.." (PMID 35432300, 2022). "Enhancer of zeste homolog 2 (EZH2) is an epigenetic regulator that plays an essential role in immune system development and autoimmune diseases." (PMID 35795677, 2022). "For example, in mice with Treg-selective deletion of CD28, Ubc13, Helios or Ezh2, impaired Treg in vivo suppressive activity is accompanied by development of spontaneous autoimmune diseases, yet in vitro Treg inhibitory function remained normal." (PMID 33024109, 2020). "Several studies have evaluated the role of EZH2 in the regulation of T cell differentiation and plasticity as well as its implications in the development of autoimmune diseases and graft-versus-host disease (GVHD)." (PMID 27199994, 2016). "Numerous studies have evaluated the role of EZH2 in the regulation of T cell differentiation and plasticity as well as its implications in the development of autoimmune diseases and graft-versus-host disease (GVHD)." (PMID 27199994, 2016). "Conversely, in autoimmune diseases, EZH2 can promote ferroptosis by inhibiting SLC7A1149." (PMID 41372608, 2025). "The therapeutic potential of EZH2 inhibitors has been shown in autoimmune diseases." (PMID 35795677, 2022). "However, active clinical investigations of EZH2 inhibitors in patients with cancer will shed new light on the future development of EZH2-targeted therapies for patients with autoimmune diseases." (PMID 36220996, 2022). "The aim of this review is to summarize the current knowledge regarding the role of EZH2 in the regulation of the differentiation and function of T cells focusing on possible applications in various immune-mediated conditions, including autoimmune disorders and GVHD." (PMID 27199994, 2016). "Further studies will be required to clarify the effects of EZH2 on the differentiation, survival, and function of Th, T effector, and Tregs in order to create novel therapeutic strategies in the area of autoimmune diseases, allogeneic transplantation, and cancer." (PMID 27199994, 2016). "In addition to SLE, EZH2 is involved in other autoimmune diseases, including autoimmune hepatitis." (PMID 36220996, 2022). "The complex actions of EZH2 on innate immune responses are important to consider with the availability of drugs targeting this epigenetic regulator in patients for cancer indications, and suggestions of a role in managing autoimmune disease such as multiple sclerosis." (PMID 34464475, 2021). "Therefore, Ezh2 may represent a potential target to modulate the tolerogenic properties of DCs in the setting of autoimmune diseases." (PMID 32899608, 2020). "In this context, EZH2 inhibitors might promote IFN-γ-producing T cells and can be used in order to enhance anti-tumor immunity, while EZH2 activating agents might serve as promising therapies for the suppression of Th1- and Th2-dependent autoimmune diseases." (PMID 27199994, 2016).
cardiac hypertrophy (15 papers, 2016 to 2024). "Our findings reveal the profile of EZH2-associated ncRNAs upon hypertrophic stimulation, and imply a dynamic regulation of EZH2 function in cardiac hypertrophy." (PMID 33732733, 2021). "Our findings reveal the landscape of EZH2-associated ncRNAs during early cardiac hypertrophy and provide novel insights into the dynamics of EZH2-mediated epigenetic remodeling." (PMID 33732733, 2021). "Nevertheless, EZH2 loss-of-function targeted to RV cardiomyocytes was shown to induce cardiac hypertrophy and fibrosis." (PMID 33803922, 2021). "For example, the lncRNA Chaer (cardiac-hypertrophy-associated epigenetic regulator) directly interacts with EZH2 to alter PRC2 targeting, which ultimately inhibits H3K27me3 at the promoter regions of genes implicated in cardiac hypertrophy." (PMID 29670886, 2018). "In Ezh2-deficient adult hearts, fetal genes are upregulated, giving rise to cardiac hypertrophy." (PMID 33732733, 2021). "Other studies have demonstrated that EZH2 is involved in cardiac hypertrophy, ROS generation, and inflammation." (PMID 38580969, 2024). "The intersection of these databases yielded genes known to be involved in cardiac hypertrophy, including EZH2, NFATc4, GATA4, and JARID2." (PMID 38810124, 2024). "Chaer is required for the development of cardiac hypertrophy through direct binding with PRC2 subunit EZH2 to further regulate expressions of Anf, Myh7 and Acta1 genes." (PMID 34604357, 2021). "The dynamic interaction between EZH2 and ncRNAs suggests a complex role of EZH2 in the pathogenesis of cardiac hypertrophy." (PMID 33732733, 2021). "Our previous study revealed that lncRNA Chaer transiently interacted with EZH2 at the early phase of cardiac hypertrophy." (PMID 33732733, 2021). "Luciferase assays confirmed that miR-214 targeted the 3′-UTR of Ezh2, a repressor of cardiac hypertrophy." (PMID 34943783, 2021). "Taken together, our study provides direct evidence for the complex role of EZH2 during early cardiac hypertrophy, and unveils a novel access to modify EZH2 function through ncRNAs." (PMID 33732733, 2021). "This is consistent with our previous report that Chaer-EZH2 interaction was transiently enhanced at the early phase of cardiac hypertrophy and that overall H3K27me3 was quickly diminished upon hypertrophic stimulation." (PMID 33732733, 2021). "Enhancer of zeste 2 (EZH2) governs gene reprogramming during cardiac hypertrophy through epigenetic remodeling, a process regulated by numerous non-coding RNAs (ncRNAs)." (PMID 33732733, 2021). "Uc.323 protects CMs against cardiac hypertrophy by binding with EZH2 to regulate CPT1b gene expression." (PMID 34604357, 2021). "Inactivation of Ezh2 in a subpopulation of anterior heart field cardiac progenitor cells results in failure to down-regulate fetal gene programs, leading to cardiac hypertrophy during adulthood." (PMID 29466371, 2018). "Targeting of Ezh2 is also consistent with studies on cardiac hypertrophy." (PMID 34943783, 2021). "In a mouse model of cardiac hypertrophy, pri-miR-208b could directly bind to polycomb group protein enhancer of zeste 2 polycomb repressive complex 2 subunit (EZH2) and mediate the silencing of hypertrophic genes." (PMID 31491855, 2019). "G9a, H3K9 histone methyltransferase, combined with enhancer of zeste homolog 2 (EZH2) and transcription factor myocyte-specific enhancer factor 2C (MEF2C), inhibits the transcription of antihypertrophic genes, thereby promoting cardiac hypertrophy." (PMID 37063966, 2023). "In conclusion, our study revealed that CaMKII is a new target of suppression by EZH2-mediated H3K27me3 and is epigenetically inhibited by TINCR, which will provide a novel therapeutic strategy for cardiac hypertrophy." (PMID 28548932, 2017). "Although EZH2 was reported to inhibit cardiac hypertrophy by recruiting H3K27me3 on prohypertrophic genes like ANP, BNP, and CaMKII, it remains obscure how EZH2 may contribute to the pathogenesis of TAC-induced PAH." (PMID 29854032, 2018).
Hyperglycemia (15 papers, 2017 to 2025). An increased concentration of glucose in the blood. "This is supported by our observation in a well-established model of hyperglycemia treated EC where we had previously reported activation of EZH2-H3K27me3 axis causing endothelial inflammation." (PMID 40289112, 2025). "Previous studies from our lab report deposition of H3K27me3 marks in human umbilical vein endothelial cells (HUVEC) exposed to intermittent hyperglycemia caused by a reduction in EZH2 threonine 367 phosphorylation and nuclear retention of EZH2." (PMID 35392173, 2022). "We have previously reported that maternal hyperglycemia or increasing the levels of total O-GlcNAc also increased EZH2-Thr311p levels." (PMID 39798880, 2025). "Hyperglycemia challenge increased the level of EZH2 and H3K27me3 in both cultured EC and rat aorta which was reversed upon GSNO exposure." (PMID 40289112, 2025). "EZH2-mediated H3K27me3 represents a key epigenetic driver of hyperglycemia-induced endothelial dysfunction." (PMID 38580969, 2024). "Such reduction in EZH2 protein level was also apparent in cells that were exposed to intermittent hyperglycemia." (PMID 34685528, 2021). "Changes in histone patterning upon hyperglycemia govern an inflammatory switch of EC through the EZH2–H3K27me3 axis, and inhibition of said epigenetic pathway alters the course of the EC inflammatory switch." (PMID 34685528, 2021). "Increased H3K27me3 (histone H3 trimethylated at lysine 27) levels and more recruitment of Enhancer of zeste homolog 2 (EZH2) at the MMP-9 promoter has been detected in Hyperglycemia." (PMID 32695308, 2020). "Hyperglycemia increased the levels of H3K27me3 and recruitment of enhancer of zeste homolog 2 (EZH2) at the MMP-9 promoter." (PMID 33537003, 2020). "Using human retinal endothelial cells, and also retinal microvessels from diabetic rats, effect of hyperglycemia on H3K27me3, and recruitment of Ezh2 at the MMP-9 promoter were quantified by chromatin-immunoprecipitation technique." (PMID 29261844, 2017). "Hyperglycemia elevated H3K27me3 levels and the recruitment of Ezh2 at the MMP-9 promoter, and increased the enzyme activity of Ezh2." (PMID 29261844, 2017). "Furthermore, administration of GSNO in the same model attenuated hyperglycemia-induced EZH2-H3K27me3 activation, endothelial inflammation and further diminished monocyte adhesion both in vitro and ex vivo." (PMID 40289112, 2025). "Furthermore, such catalytic deactivation through S-nitrosylation of EZH2 also reversed hyperglycemia-induced endothelial inflammation and monocyte adhesion." (PMID 40289112, 2025). "Furthermore, in a disease setting, we also reported the reversal of hyperglycemia-driven endothelial inflammation upon S-nitrosylation of EZH2." (PMID 40289112, 2025). "In the same study, we reported that suppression of eNOS upon hyperglycemia was one of the key drivers of endothelial inflammation, however, we did not evaluate whether such downregulation of eNOS could in turn regulate EZH2 stability and function." (PMID 40289112, 2025). "To determine the potential mechanisms by which hyperglycemia promotes myocardial fibrosis, we conducted the expression of CaN/NFATc3 pathway and a potential downstream protein of this signaling, EZH2, in the diabetic heart tissues and NRCFs exposed to high glucose for 72 h." (PMID 37735624, 2023). "While the study was limited to in vitro demonstration of EZH2 inhibition, future studies will need to account for heterogeneity in cell populations, as well as investigating the ability to reverse hyperglycaemia in pre-clinical models whilst further characterizing the responsive-regenerative cells." (PMID 37309004, 2023). "Moreover, we have recently shown that hyperglycemia and increased global protein O-GlcNAc levels increased EZH2-Thr311p in human embryonic stem cell-neuronal differentiation in cell culture leading to reduced H3K27me3 levels at several neurodevelopmental genes." (PMID 39798880, 2025).
Hyperglycemia (continued). "EZH2-mediated regulation of gene expression through its H3K27me3 catalytic activity is well known to control the pathogenesis of different diseases; however, how such mechanisms drive endothelial inflammation and its dysfunction upon hyperglycemia challenge is not clearly understood." (PMID 34685528, 2021). "However, the role of EZH2 and its associated catalytic product H3K27me3 in hyperglycemia-induced endothelial dysfunction and apoptosis has not yet been explored." (PMID 34685528, 2021).
Intellectual disability (15 papers, 2016 to 2025). "For example, variants in PRC2 members EED, SUZ12 and EZH2 share a similar DNAm signature, and a similar clinical spectrum characterised by overgrowth and intellectual disability." (PMID 39843918, 2025). "In this research, EZH2 is downregulated in hippocampal tissues in DS versus control samples, which implied that EZH2 also play roles in neurological deficiency of DS especially in intellectual disability." (PMID 27266699, 2016). "Mutations in the genes encoding other components of PRC2, namely EZH2 and EED, also lead to overgrowth, macrocephaly, advanced bone age, variable intellectual disability and distinctive facial features." (PMID 34681033, 2021). "The genetic variation of EZH2-a chromatin remodeling factors is observed in intellectual disabilities and ASD." (PMID 33080834, 2020).